ENSG00000255639 (novel protein)
Gene: Protein-coding gene on chromosome 12 (4,649,101 to 4,774,184, forward strand). Ensembl gene ENSG00000255639.
Genetic constraint (gnomAD): Loss-of-function variants: 32 observed, 43.8 expected, observed/expected ratio (o/e) 0.73, 90% interval 0.55 to 0.98. Missense variants: 540 observed, 563.59 expected, observed/expected ratio (o/e) 0.96, 90% interval 0.89 to 1.03. Synonymous variants: 206 observed, 200.34 expected, observed/expected ratio (o/e) 1.03, 90% interval 0.92 to 1.15.